ERICH3 (glutamate rich 3)
Description:
Component of the primary cilium that controls cilium formation and length. May function within retrograde intraflagellar transport (IFT)-associated pathways to remove signaling proteins from primary cilia. Also involved in neuronal vesicle biogenesis and neurotransmitter vesicular function.
Synonyms: C1orf173; DKFZp547I048; RP11-653A5.1
Tractability: PROTAC: ubiquitination databases record sites on it.
Gene: Protein-coding gene on chromosome 1 (74,568,117 to 74,673,792, reverse strand). Ensembl gene ENSG00000178965.
Subcellular location: Cell projection, cilium; Cytoplasm; Cytoplasm, cytoskeleton, cilium axoneme
Subcellular location (Human Protein Atlas): Endoplasmic reticulum; Nuclear membrane; Nucleoli; Primary cilium
Gene Ontology:
Biological process: cilium assembly
Cellular component: axoneme; cilium; cytoplasm; non-motile cilium
Genetic constraint (gnomAD): Loss-of-function variants: 111 observed, 116.1 expected, observed/expected ratio (o/e) 0.96, 90% interval 0.82 to 1.12. The upper end of that interval is the gene's LOEUF score, 1.12, which puts it in group 4 of 6, group 1 being the genes least tolerant of losing a copy. Missense variants: 1,952 observed, 1,777.3 expected, observed/expected ratio (o/e) 1.1, 90% interval 1.06 to 1.14. Synonymous variants: 656 observed, 643.01 expected, observed/expected ratio (o/e) 1.02, 90% interval 0.96 to 1.09.
Homologues: Orthologues: chimpanzee ERICH3 (98% identical), macaque CRYZ (90% identical), rabbit ERICH3 (59% identical), mouse Erich3 (49% identical), rat Erich3 (49% identical), guinea pig Erich3 (48% identical), tropical clawed frog erich3 (28% identical), dog ERICH3 (26% identical), zebrafish erich3 (17% identical).
Diseases named in the same sentence as ERICH3 in open-access papers:
ERICH3 is named in the same sentence as 11 diseases in open-access papers, as found by Europe PMC text mining. Sharing a sentence is not in itself a finding about the gene and the disease. The quoted sentences say what the papers report.
depression (4 papers, 2019 to 2024). "Taken together, these observations suggest that ERICH3 might be related to risk for psychiatric disorders such as depression and schizophrenia." (PMID 33230203, 2021). "Furthermore, our finding of a ciliary role for ERICH3 raises the possibility that ciliary dysfunction may at least partially underlie reported associations of ERICH3 with major depression disorder, osteoporosis and colorectal cancer." (PMID 31712586, 2019). "The ERICH3 gene, for which no PPI network could be established, is associated with a negative response to the treatment of depression with selective serotonin reuptake inhibitors (SSRIs) in subjects with AD." (PMID 39062884, 2024).
neuroblastoma (2 papers, 2020 to 2021). Neuroblastoma (NB) is the most common solid, extracranial childhood tumor. "Knocking down TSPAN5 and ERICH3 resulted in decreased 5-HT concentrations in neuroblastoma cell culture media and decreased expression of enzymes involved in 5-HT biosynthesis and metabolism." (PMID 33510640, 2020). "To help determine how ERICH3 might influence 5-HT concentrations, both within the cell and in cell culture media, we performed a series of experiments using SK-N-SH neuroblastoma cells." (PMID 33230203, 2021). "In addition, our results with regard to the role of ERICH3 in 5-HT biology were obtained using SK-N-SH neuroblastoma cells, results that will also require validation using serotonergic neurons once the technology to culture that type of neuron becomes less challenging technically." (PMID 33230203, 2021).
alcohol use disorder (1 paper, 2020). "Functional genomic studies demonstrated that ERICH3 was involved in clathrin-mediated vesicle formation and TSPAN5 was an ethanol-responsive gene that may be a marker for response to acamprosate pharmacotherapy of alcohol use disorder (AUD), a neuropsychiatric disorder highly co-morbid with MDD." (PMID 33510640, 2020).
Bardet-Biedl syndrome (1 paper, 2019). A ciliopathy with multisystem involvement. "Given that the functional interactors of ERICH3 are all associated with ciliary diseases such as Joubert syndrome (ARL13B, INPP5E) and Bardet Biedl syndrome, ERICH3 represents an attractive candidate for mutations in unresolved ciliopathies." (PMID 31712586, 2019).
nasopharyngeal carcinoma (1 paper, 2022). A carcinoma arising from the nasopharyngeal epithelium. "HACL1 is closely related to small-cell lung cancer, and ERICH3 may be a key biomarker in nasopharyngeal carcinoma." (PMID 35252170, 2022).
schizophrenia (1 paper, 2021). A major psychotic disorder characterized by abnormalities in the perception or expression of reality. "Transcriptome data generated by the PsychENCODE project also showed that ERICH3 mRNA was elevated in postmortem human brain samples from subjects with schizophrenia (FDR = 0.01)." (PMID 33230203, 2021).
ERICH3 also shares sentences with these, for which no sentence is quoted: ciliopathies (1 paper); glioma (1); Joubert syndrome (1); osteoporosis (1); small cell lung carcinoma (1).